ALB (albumin)
Diseases named in the same sentence as ALB in open-access papers (continued):
Sharing a sentence is not in itself a finding about the gene and the disease.
neuroblastoma (12 papers, 2016 to 2026). Neuroblastoma (NB) is the most common solid, extracranial childhood tumor. "To initially examine how the properties of L2-siRNA might impact CSF to brain delivery, we evaluated in vitro uptake in neuroblastoma cells and ex vivo association with albumin in CSF, with comparisons to unconjugated siRNA (“siRNA”) and cholesterol-conjugated siRNA (“Chol-siRNA”)." (PMID 40598893, 2025). "Additional studies tested the efficacy of improving membrane repair when mouse neuroblastoma cells (N2A) were exposed to AD patient CSF with the application of 1 μM bovine serum albumin (BSA) as a control or 1 μM rhMG53." (PMID 40149954, 2025). "Here, we here investigated the effects of doxorubicin-loaded human serum albumin (HSA) nanoparticles in ABCB1-expressing neuroblastoma cells." (PMID 31501742, 2019). "Here, we tested doxorubicin-loaded human serum albumin (HSA) nanoparticles in the neuroblastoma cell line UKF-NB-3 and its ABCB1-expressing sublines adapted to vincristine (UKF-NB-3rVCR1) and doxorubicin (UKF-NB-3rDOX20)." (PMID 31501742, 2019). "To investigate if SPARC mediated the increased deposition of lipids in neuroblastoma tumors by binding and transporting albumin loaded with FA, we characterized the interaction between the two proteins." (PMID 27776337, 2016). "Based on these issues, by using Western blot and different cell lines including N2a mouse neuroblastoma cells, HT22 murine hippocampal neuronal cells and BV2 murine microglial cells, we compared the expression levels of albumin in these cell lines." (PMID 33397436, 2021). "Albumin nanoparticles and liposomes were prepared and characterized regarding size and ζ-potential distribution, polidispersity index, entrapment efficiency and activity against SH-SY5Y human neuroblastoma cell line." (PMID 26898318, 2016). "We found that palmitate induced significant lipotoxicity in neuroblastoma cell lines cultured in hypoxic conditions, suggesting that SPARC may promote lipotoxicity and neuroblastoma cell death by increasing the delivery of albumin-bound FA." (PMID 27776337, 2016). "With the aim to obtain a site-specific doxorubicin (DOX) delivery in neuroblastoma SH-SY5Y cells, we designed an hybrid nanocarrier combining graphene oxide (GO) and magnetic iron oxide nanoparticles (MNPs), acting as core elements, and a curcumin–human serum albumin conjugate as functional coating." (PMID 30583524, 2018).
oral squamous cell carcinoma (12 papers, 2018 to 2024). "This study investigated preoperative neutrophil percentage-to-albumin ratio (NPAR) for predicting oral cavity squamous cell carcinoma (OSCC) survival." (PMID 36230814, 2022). "Similarly to previous study, elevated CRP/ALB ratio was observed in oral squamous cell carcinoma patients with poor overall survival." (PMID 35982996, 2022). "Then, the AGR, defined as ALB (g/L)/GLB (g/L), proved to be an independent prognostic factor in digestive system cancers, upper-tract urothelial carcinoma, and oral squamous cell carcinoma." (PMID 36983238, 2023). "A novel scoring system based on albumin and the neutrophil-to-lymphocyte ratio (NLR) was developed and incorporated into a nomogram to create a more accurate prognostic tool for oral cavity squamous cell carcinoma (OSCC) patients." (PMID 30166572, 2018). "Although the C-reactive protein-to-albumin ratio (CAR) can predict poor outcomes in assorted cancers, its prognostic value in oral cavity squamous cell carcinoma (OSCC) remains unclear." (PMID 32587804, 2020).
respiratory infection (12 papers, 2015 to 2025). "From the analysis of the research results, it was found that low albumin ≤2.5 g/dL, respiratory infection, and antibiotic treatment ≥1 h are significantly associated with the incidence of DIC in septic patients." (PMID 36362708, 2022). "Low albumin levels, respiratory infection, and antibiotic administration >1 h are associated with DIC development in septic patients." (PMID 36362708, 2022). "Low albumin, respiratory infection, and antibiotic treatment ≥1 h were found to be risk factors for development of DIC in septic patients." (PMID 36362708, 2022). "Logistic Regression modeling in cohort 1 identified nine independent risk factors, including smoking, respiratory infection in the last month, preoperative antibiotic use, preoperative saturation of peripheral oxygen, surgery site, blood lost, postoperative blood glucose, albumin, and ventilation." (PMID 25821791, 2015). "In the multivariate analysis, albumin ≤2.5 g/dL (OR: 2.363; 95% CI: 1.201–4.649), respiratory infection (OR: 2.414; 95% CI: 1.046–5.571), and antibiotic treatment ≥1 h (OR: 2.181; 95% CI: 1.014–4.689) were associated with DIC development." (PMID 36362708, 2022). "Nine independent risk factors were finally selected to participate in the brief predictive index for PPCs, including smoking, respiratory infection in the last month, antibiotic use, SpO2, surgery site and blood lost, blood glucose, albumin, and ventilation." (PMID 25821791, 2015). "Additional risk factors for the development of infections among colonized patients include colonization at multiple sites, polymicrobial etiology, antibiotic use within the past 90 days, concurrent respiratory infections, albumin administration, catheterization, and other invasive procedures." (PMID 40284612, 2025). "Our study found that albumin was clinically relevant to the occurrence of respiratory infection." (PMID 34488717, 2021). "Other outcomes of respiratory infections that improved after switching from cigarettes to IQOS included inflammatory T-cell infiltration into the lungs, the content of total proteins accumulated in BAL, and albumin leak." (PMID 39427167, 2024). "In the univariate Cox regression analysis, an inability to ambulate, respiratory infection, CRP level, albumin level and CAR were found to have statistically significant effects on the 28-day survival rate (p = 0.031, p = 0.043, p < 0.001, p = 0.013 and p < 0.001)." (PMID 35962331, 2022).
varices (12 papers, 2018 to 2024). "In our population, the combined criteria based on platelet count and serum albumin performed well, saving 30-40% of EGDs and correctly identifying 99.1% of patients who could safely avoid screening endoscopies for high-risk varices in compensated cirrhotic patients." (PMID 32766309, 2020). "Among the patients with albumin globulin reversal, 52.4% had varices, while only 33% of those with normal albumin globulin ratio had varices that were significant with a p-value of 0.024." (PMID 37565128, 2023). "In patients with low albumin (<3 g/dL), 60.4% had varices, 47.6% of patients with albumin between 3 and 3.5 g/dL had varices, and only 29.5% of those with albumin >3.5 g/dL had varices with a statistically significant p-value of 0.001." (PMID 37565128, 2023). "Patients with cACLD had lower prevalence of varices, lower MELD score, HVPG, LSM, as well as higher plasma sodium and plasma albumin levels as compared to patients with dACLD." (PMID 36653504, 2023).
Acidosis (11 papers, 2009 to 2025). Abnormal acid accumulation or depletion of base. "Acidosis caused by accumulation of UMAs can be detected using SIG, which can be accurately reflected by AG corrected for serum albumin." (PMID 28328963, 2017). "Metabolic acidosis inhibits albumin synthesis, so serum albumin content and SID, which both increased during LPVD, refer together to decreased acidosis." (PMID 23181739, 2012). "Data on paracetamol and flucloxacillin prescriptions and laboratory data (pH, Na+, HCO3−, Cl−, albumin and 5-oxoproline levels) were combined to assess the prevalence of acidosis, calculate the anion gap and analyse 5-oxoproline levels in clinically admitted patients using both drugs simultaneously." (PMID 28782093, 2017). "Bronchopneumonia presented with respiratory acidosis, while in some patients metabolic alkalosis with low albumin levels pointed out to the fact that respiratory acidosis may be compensated by metabolic alkalosis." (PMID 20859489, 2010).
albuminuria (11 papers, 2017 to 2025). The presence of albumin in the urine, an indicator of KIDNEY DISEASES. "Albuminuria is considered to be the result of an increased glomerular filter permeability and disrupted tubular absorption of albumin." (PMID 36836700, 2023). "Albuminuria is diagnosed when excretion of albumin, measured as albumin-to-creatinine ratio, rises to levels above 20 and 30 mg/g creatinine in men and women, respectively." (PMID 36768208, 2023). "For instance, the biomarker target “Albuminuria” was best predicted in females using body mass index (BMI), high-density lipoprotein (HDL), waist circumference, triglycerides, uric acid, and urine albumin-to-creatinine ratio (UrAlbCr)." (PMID 40593815, 2025).
aneurysm (11 papers, 2010 to 2026). Bulging or ballooning in an area of an artery secondary to arterial wall weakening. "If the endothelial barrier between blood and the extravascular space is not intact, e.g., as a result of the loss of endothelial cells, albumin-bound gadofosveset leaks into the extravascular aneurysm wall." (PMID 32094414, 2020). "Univariate analysis showed that hemorrhagic presentation, admission mRS score, AVM volume, deep location, deep venous drainage, associated aneurysms, glucose, albumin, TC, and Hcy were related to the neurological outcome." (PMID 33312268, 2020). "In addition, albumin deficiency promotes a hypercoagulable state (elevated fibrinogen) and microthrombus formation, while impaired NO metabolism triggers vasospasm, collectively aggravating the risk of coronary ischemia and aneurysm." (PMID 40364829, 2025). "Given that the significant association between high UAR level and poor prognosis of aSAH, UA and ALB may be novel therapeutic targets for aneurysm patients." (PMID 41602990, 2026). "Non-responder patients had a higher proportion of aneurysms (15% vs 8%), lower hemoglobin, albumin and sodium in serum and higher maximum platelet and leucocyte count, higher creatinine, and procalcitonin in serum." (PMID 31107862, 2019). "The another patient was input into the model: with age 55 years, the GCS score at admission was 13, albumin level 36.9 g/L, D-dimer lever 2.68 ug/ml, AISI 3560, without aneurysm located in the MCA." (PMID 41368359, 2025).
autoimmune encephalitis (11 papers, 2018 to 2026). Inflammation of the brain secondary to an immune response triggered by the body itself. "Several studies have shown that albumin is also associated with the severity and prognosis of autoimmune encephalitis." (PMID 35479085, 2022). "We investigated whether serum albumin was associated with the treatment response of early immune therapies, including IVIg and rituximab, in patients with autoimmune encephalitis." (PMID 29343812, 2018). "In line with this, low albumin is suggested as a poor prognostic factor in Guillain–Barré syndrome, and high albumin indicates a good prognosis of autoimmune encephalitis." (PMID 40806813, 2025). "Increased albumin quotient and IgG.Autoimmune encephalitis antibody, paraneoplastic antibody, and oligoclonal band negative." (PMID 39445192, 2024). "The mean albumin quotient was highest in the “other neuropsychiatric” group (4.5 x 10–3) although those with autoimmune encephalitis had a similar proportion of subjects with abnormally elevated levels (25%)." (PMID 39224487, 2024). "Some studies have also confirmed that albumin is a factor affecting the progression of immune diseases such as Guillain–Barre syndrome and autoimmune encephalitis." (PMID 35479085, 2022). "Seventeen (53.1%) of the 32 patients with definite autoimmune encephalitis who received IVIg treatment in our hospital had low serum albumin (<4.0 g/dL)." (PMID 29343812, 2018). "We evaluated serial serum albumin and its changes between time intervals in autoimmune encephalitis patients." (PMID 29343812, 2018). "Further studies are needed to validate the clinical implication of serum albumin in the treatment of autoimmune encephalitis." (PMID 29343812, 2018). "The initial disease severity (mRS ≥ 4) was the sole factor that predicted low albumin in autoimmune encephalitis patients using multivariate analysis (P = 0.013)." (PMID 29343812, 2018). "We demonstrated that autoimmune encephalitis patients with low serum albumin (<4.0 g/dL) exhibited poor initial response to immune therapies at the third and fourth weeks after IVIg treatment compared to the high albumin patients." (PMID 29343812, 2018). "Multivariate analysis demonstrated that the initial disease severity (mRS ≥ 4) was the sole factor that predicted low albumin in autoimmune encephalitis patients (P = 0.013)." (PMID 29343812, 2018). "Seventeen (53.1%) of the 32 patients with definite autoimmune encephalitis who received IVIg treatment in our hospital exhibited low serum albumin (<4.0 g/dL)." (PMID 29343812, 2018). "Our study found that pretreatment low serum albumin was a significant indicator of autoimmune encephalitis prognosis in the short-term and long-term." (PMID 29343812, 2018). "In summary, our study found that low pretreatment serum albumin was a significant indicator of the short-term and long-term prognosis of autoimmune encephalitis." (PMID 29343812, 2018). "Thus, we investigated serum albumin as a prognostic biomarker of early immune therapies in patients with autoimmune encephalitis." (PMID 29343812, 2018). "Serum albumin in autoimmune encephalitis strongly correlated with the initial patient presentation." (PMID 29343812, 2018). "In neuropsychiatric systemic lupus erythematosus (SLE) and autoimmune encephalitis (AE), normal studies do not rule out disease, although CSF total protein, albumin quotient, and IgG index can be abnormal and aid in diagnosis." (PMID 39224487, 2024). "Moreover, BMI did not correlate with the low albumin in autoimmune encephalitis, as observed in patients with heart failure." (PMID 29343812, 2018).
brain cancer (11 papers, 2014 to 2025). A primary or metastatic malignant neoplasm affecting the brain. "This review article provides a new comprehensive analysis of albumin-based nanoparticles that have been used in research studies for the diagnosis and treatment of brain cancer." (PMID 37836018, 2023). "There is ongoing and consistent research on the advancement of albumin-based nanoparticles to treat brain cancer." (PMID 37836018, 2023). "Scientists must take an interdisciplinary approach to develop multifunctional, next-generation albumin-based delivery systems to treat brain cancer." (PMID 37836018, 2023). "Glioma 261 (GL261) and brain cancer stem cells were targeted with temozolomide acid (TMZA) encapsulated into human serum albumin nanoparticles (HSA NPs)." (PMID 35999629, 2022). "The albumin is especially beneficial for brain cancer treatments because of albumin binding receptors, such as SPARC and gp60, overexpressed on gliomas." (PMID 30499047, 2018). "One of the most widely used protein-based nanoformulations in the therapeutic studies of brain cancers involves the use of serum albumin, possibly due to the high energy/nutrient requirement-induced overexpression of albumin binding proteins (e.g., gp60) on cancerous cells." (PMID 36358807, 2022). "The most abundant proteins were: uncharacterized proteins (11.3%), transferases (6.9%), actin (6.8%), albumin (6.4%), dehydrogenases (4.4%), deleted in malignant brain tumors (2.5%), kinase (2.4%), myosin (2.2%), aldolases (2.1%), enolases (2.0%) and peroxidases (2.0%)." (PMID 32767984, 2020). "The LMWP-modified albumin-based nanoparticle system was designed to co-administrate PTX and 4 HPR, both used in brain cancer therapy." (PMID 37836018, 2023). "They identified preoperative SII, albumin-bilirubin grade, and combined SII and PNI (COSII-PNI) as reliable prognostic indicators for patients undergoing surgical resection for malignant brain tumors." (PMID 37873542, 2023). "In addition, since preoperative serum albumin levels in patients with malignant brain tumors could positively affect the survival curve, it can be assumed that injecting exogenous albumin into the body can help the patient’s postoperative recovery as well as effective FGS progression." (PMID 36614294, 2023).
Cholecystitis (11 papers, 2015 to 2023). The presence of inflammatory changes in the gallbladder. "A low serum albumin level may be a risk factor for delayed diagnosis of cholecystitis." (PMID 36295553, 2022). "We found that high serum albumin levels are related to early diagnosis of cholecystitis among older admitted patients." (PMID 36295553, 2022). "Clinicians should be concerned about delayed diagnosis of cholecystitis in older female patients with poor nutritional status, such as low serum albumin levels, and in patients with a low BMI and vague symptoms without abdominal pain." (PMID 36295553, 2022). "The results show that a low serum albumin level might be related to delayed diagnosis, while male sex, the presence of abdominal pain, and high BMI showed trends toward early cholecystitis diagnosis." (PMID 36295553, 2022). "Serum albumin levels could be affected by various metabolic factors, which might mask the symptoms of cholecystitis, except for abdominal pain." (PMID 36295553, 2022). "Clinicians should consider the possibility of cholecystitis in older female patients with poor nutritional status, such as low serum albumin levels, low BMI, and vague symptoms without abdominal pain." (PMID 36295553, 2022). "Clinicians should be concerned about the delay in cholecystitis diagnosis in older female patients with poor nutritional conditions, including low serum albumin levels, a low BMI, vague symptoms, and no abdominal pain." (PMID 36295553, 2022). "In terms of laboratory indicators, those reflecting liver anabolism and reserve function, including albumin (ALB), total bile acid (TB), bilirubin, cholinesterase (CHE), and prothrombin activity (PTA), were significantly lower in the cholecystitis group than in the cholecystitis group." (PMID 37095526, 2023). "Albumin, total bile acid, bilirubin, cholinesterase, and prothrombin activity in patients with cholecystitis were significantly inferior to those in patients without cholecystitis (P < 0.001, P < 0.001, P < 0.001, P < 0.001 and P = 0.003, respectively)." (PMID 37095526, 2023). "A cohort study showed that older female patients with poor nutritional conditions, including low serum albumin levels, low BMI, vague symptoms and no abdominal pain might have delayed cholecystitis diagnosis." (PMID 37875814, 2023). "Interestingly, the indicators that reflected the anabolic capacity of the liver, such as ALB, CHE, TB, and PTA were significantly lower than those in the group without cholecystitis." (PMID 37095526, 2023).